TNF (tumor necrosis factor)
Diseases named in the same sentence as TNF in open-access papers (continued):
Sharing a sentence is not in itself a finding about the gene and the disease.
Sepsis (continued). "ELISA results revealed that, compared to the normal group, the protein levels of TNF-α, IL-6, IL-10, and MCP-1 were increased in the sepsis model (P < 0.05)." (PMID 38961068, 2024). "In the early stage of sepsis, monocytes/macrophages are rapidly recruited and release many inflammatory cytokines (e.g. IL-1β, IFN-γ, IL-6, TNF-α, and IL-10); subsequently, chemokines are released and acted on involved organs." (PMID 39320524, 2024). "Pro-inflammatory cytokines, mainly TNF-α, upregulate the expression of both ICAM-1 and VCAM-1, and these adhesion molecules are highly expressed in endothelial cells during sepsis." (PMID 38254684, 2024). "Since 1982, scientists have conducted extensive preclinical research on molecular-targeted therapies for sepsis, including corticosteroids, TLR4 receptor antagonists, anti-TNF-α agents, and interventions targeting cytotoxic effects and the coagulation cascade." (PMID 38690282, 2024). "For instance, while anti-TNF therapies might improve outcomes in cases involving endotoxins or specific bacteria like Staphylococcus aureus, they show limitations in more complex scenarios involving polymicrobial infections, as seen in models of sepsis induced by cecal ligation and puncture." (PMID 39056754, 2024). "In this study, we constructed a predictive model for NOAF in sepsis using MPO and HOCl combined with TNF-α, WBC, and APACHE II score, which demonstrated a better predictive value with an AUC of 0.897." (PMID 39030470, 2024). "As a result of the judicious selection of electrode design, it is possible to detect sepsis biomarkers with unprecedented sensitivity, reaching LODs of 0.82 ag mL−1 for PCT, 0.167 ng mL−1 for CRP, 0.202 pg mL−1 for TNF-α, and 0.056 fg mL−1 for IL-6." (PMID 38920613, 2024). "Compared to both the vehicle and sepsis groups, a single dose of ghrelin administered immediately after the CLP procedure significantly (P <0.001) lowered serum TNF-α levels." (PMID 39144689, 2024). "In a murine model of polymicrobial sepsis, the exogenous administration of an anticoagulant antibody that selectively blocks FXI activation by FXII led to reduced IL-6 and TNF-a, reduced PLT consumption, and improved overall survival." (PMID 39337090, 2024). "HMGB1 has been known to induce the production of cytokines like TNF-α, IL-1β, and IL-6 through various mechanisms, including the NF-κB and ERK 1/2 pathways, exacerbating the pathological condition of sepsis." (PMID 38474222, 2024). "The mean serum levels of TNF-α, MIF, TLR4, and 8-epi-PGF2α levels were significantly higher in the sepsis and vehicle groups than in the normal and sham groups." (PMID 39144689, 2024). "Our study showed that the serum levels of TNF-α and MIP-1α in the LPS groups were higher than those in the control groups, suggesting that inflammatory reaction occurred in the LPS groups during sepsis." (PMID 39178201, 2024). "Let-7b has been found to inhibit pro-inflammatory responses, especially IL-6 and TNF, by suppressing the TLR4/NFkB pathway in a mouse model of sepsis." (PMID 38400048, 2024). "The cecal gene expression of IL-6, IL-1β, TNF-α, IL-17A, IL-22, and CRAMP (homologue of human cathelicidin LL-37) was significantly elevated in mice with gut-derived P. aeruginosa sepsis." (PMID 38790988, 2024). "This systemic inflammation, often observed in conditions such as sepsis, is characterized by elevated levels of inflammatory markers like C-reactive protein (CRP), interleukin-6 (IL-6), and tumor necrosis factor-alpha (TNF-α)." (PMID 39563441, 2024). "The failure of corticosteroids, anti-TNF-α, and anti-interleukin-6 monoclonal antibodies can be attributed to this altered EFA metabolism in sepsis." (PMID 38929553, 2024). "Antiapoptotic activity, better modulation of macrophage function, reduction of pro-inflammatory mediators such as Interleukin 6 (IL-6) and tumor necrosis factor α (TNF-α), and inhibition of the inflammatory reaction to sepsis have also been reported." (PMID 37109010, 2023).
Sepsis (continued). "Interleukin (IL)-1β, tumour necrosis factor (TNFα), high mobility group protein 1 (HMGB1) and IL-6 are the most vital cytokines promoting the inflammatory response in sepsis and are key biomarkers of septic shock in systemic inflammatory response syndrome." (PMID 37474902, 2023). "Compared to the sham group, the sepsis group had significantly elevated levels of TLR-4, IL-6, TNF-α, MIF, F2-isoprostane, caspase-3, cTn-I, and CK-MB (p<0.05)." (PMID 37900081, 2023). "In a model of E. coli-induced sepsis, 15-epi-LXA4 presented a synergic effect with antibiotics by regulating IL-6 and TNF-α production by macrophages, thus limiting bacterial replication, neutrophil migration, and resulting in better survival rates." (PMID 37446699, 2023). "In agreement, other studies have reported lower plasma concentrations of TNF-α and IL-6 in transgenic mice expressing CETP compared to wild-types following LPS stimulation or sepsis." (PMID 37892238, 2023). "In a retrospective study involving 104 patients with sepsis, the combination of PCT, MR-proADM, and TNFα showed the best results in early sepsis detection compared to individual biomarkers." (PMID 37626802, 2023). "In our previous study, in the sepsis model induced by the cecal ligation puncture, TCE significantly reduced TNF-α, IL-1β, IL-6, TOS, OSI levels, increased TAS values, and significantly decreased caspase-3 and NF κB expression." (PMID 37476882, 2023). "Moreover, serum levels of cytokines TNF-α and IL-6 were decreased, and LPS-induced sepsis in mice and cynomolgus monkeys was relieved after the administration of these NPs, being promising candidates for the treatment of sepsis and cytokine-storm-related conditions." (PMID 36894763, 2023). "In our study, the plasma levels of proinflammatory cytokines IL-1β, IL-6 and TNF-α were markedly elevated in CLP group rats at 12 hours to 5 days, also demonstrating once again the successful establishment of a CLP-induced sepsis model." (PMID 37219401, 2023). "In the model of CLP sepsis, CTX significantly downregulated the expression of pro-inflammatory cytokines TNF-α and IL-6, and increased the ratio of lipoxin A4, prostaglandin E2, and IFN-γ in mice plasma." (PMID 37629199, 2023). "Our results showed that genes such as IFN-γ, TNF-α, IL-6, MIP-2, IL-10, KC (CXCL1), CCL-2, MPO, MMP9, TLR2, and LCN2 were significantly upregulated in the lungs of sepsis-induced ARDS mice compared to control mice." (PMID 37822934, 2023). "It has been indicated that proinflammatory cytokines, such as tumor necrosis factor (TNF)‐α and interleukin (IL)‐1β, are highly upregulated during sepsis‐induced ALI, contributing to vascular dysfunction and alterations in bronchomotor tone." (PMID 37619985, 2023). "This contrasts with plasma levels of other inflammatory cytokines including TNF-α and IFN-γ that rise transiently in early stages of infection and then fall towards baseline levels at later stages of sepsis." (PMID 37535121, 2023). "More than 200 biomarkers of sepsis are described, such as C-reactive protein (CRP), procalcitonin, calprotectin, and some inflammatory cytokines, e.g., tumor necrosis factor (TNF)-α and interleukin (IL)-6, IL-8, IL-10, and IL-12." (PMID 38003758, 2023). "β-blockers can down-regulate inflammatory mediators (e.g., TNF-α, IL-6, HMGB-1) in animal models of sepsis to reduce the inflammatory response as well as inhibit cardiomyocyte apoptosis." (PMID 37964887, 2023). "In an LPS-induced rat sepsis model, levels of degraded components from EGCX correlated closely with plasma TNF-α, IL-6, and coagulation biomarkers, whereas administration of unfractionated heparin (UFH) substantially alleviated EGCX injury and coagulopathy." (PMID 37350963, 2023). "In this study, the sepsis model was established by CLP, the TNF-α was detected by ELISA to reflect the infection of the animal model." (PMID 37465664, 2023).
Sepsis (continued). "TNF-α, IFN-γ, and IL-6 represent vital inflammatory mediators in the progression of lung injury in both sepsis and COVID-19 scenarios." (PMID 37822934, 2023). "We confirmed the positive correlations between the plasma levels of interleukin 1-β (IL-1β), eotaxin, interferon-α (IFN-α), tumor necrosis factor-α (TNF-α), and the reads of pathogens, and the last three remained significant in sepsis patients." (PMID 36673134, 2023). "Commonly, TNF activates Tregs through TNFR2 or IL2 signaling, leading to inflammatory reactions in autoimmunity, sepsis, infection and tumors." (PMID 37534250, 2023). "We have previously shown that A2BR-deficient mice have higher mortality and increased pro-inflammatory cytokines such as IL-6, TNF-α and MIP-2 in sepsis." (PMID 37438813, 2023). "Elevated levels of TLR2 in multiple organs of old mice augment the expression of cardiodepressant cytokines TNF-α, IL-1β, IL-6 and MCP-1 during sepsis, leading to greater cardiac dysfunction and high mortality." (PMID 38094127, 2023). "After the body suffers from burns, macrophages are overactivated into proinflammatory (M1) macrophages in the early stage of sepsis, which release inflammatory factors (IL1, IL6 and TNF‐α)." (PMID 37060578, 2023). "In rats, supplementation of lysine significantly reduced the neutrophil, lymphocyte counts, the tumor necrosis factor alpha (TNF-α), interleukin-8 (IL-8), and migration inhibitory factor (MIF) levels and protected against sepsis-induced chronic lung injury." (PMID 36968283, 2023). "Consistently, a recent study showed that levels of C-reactive protein (CRP), TNF-α, and IL-6 decreased significantly after CRRT in patients with sepsis-induced acute kidney injury (AKI)." (PMID 36650427, 2023). "In murine sepsis, RIPK1 has been shown to induce the production of GM-CSF, IL-6, IL-8, and TNF under LPS stimulation, implying that RIPK1 has a detrimental impact on sepsis." (PMID 38001795, 2023). "Treating with neutralising antibodies against TNF‐α protected mice from mortality during SARS‐CoV‐2 infection, sepsis, and cytokine shock." (PMID 37814484, 2023). "In our cohorts, NS patients showed statistically significant higher levels of inflammation, coagulation, and sepsis markers (such as NLR, CRP, ferritin, IL-6, TNF-α, D-dimer, fibrinogen, PCT, and LDH) compared to S patients." (PMID 36781931, 2023). "Multiple pathways, including the IL-17 signal pathway, the NOD-like receptor signaling pathway, and the TNF signaling pathway, were identified to be prospective targets of SIN against sepsis." (PMID 37388447, 2023). "TNF-α is widely recognized as a critical mediator in sepsis, and TLR4 plays a central role in initiating signaling pathways that lead to TNF-α production." (PMID 38001481, 2023). "In the rat model of CLP-induced sepsis, EA at ST36 significantly reduced the plasma NSE level and the expression of proinflammatory cytokines in brain tissue, such as TNF-α and IL-6, reducing brain damage." (PMID 37753078, 2023). "Statistically significant elevations in IL-6, IL1-β, TNF-α, and ANG-2 levels were found in the FIP sepsis induction group compared to the normal group." (PMID 37255096, 2023). "During endotoxin tolerance in sepsis, histone deacetylase SIRT1 accumulates on the IL-1β and TNF-α promoters, and NAD+ levels are elevated, resulting in enhanced H3K16 deacetylation." (PMID 36774341, 2023). "Compared to the sepsis and vehicle groups, the Ticagrelor-pretreated group had significantly decreased lung tissue levels of pro-inflammatory cytokines (IL-6, IL1B, and TNF-α)." (PMID 37675176, 2023). "In this study, we demonstrated that AN69ST membrane adsorbed CVVH in critically ill patients with severe sepsis and significantly decreased inflammatory parameters, including CRP, PCT, WBC, as well as secretion of inflammatory factors including IL-6 and TNF-α." (PMID 37724124, 2023).
Sepsis (continued). "Previous research showed that in sepsis, CIRP adheres to the TLR4/MD2 complex on CD8 + and CD4 + T-cells, resulting in their activation and the production of TNFα and HMGB1 from APCs." (PMID 36920542, 2023). "In our study, we observed upregulation of TNF, Toll-like receptor, and NFκB signaling pathways in LPS-induced septic heart tissues, whereas CLP-induced sepsis upregulates JAK-STAT, IL-17, and B-cell receptor signaling pathways." (PMID 37510271, 2023). "In sepsis-induced AKI, high IL-1β, IL-6, TNF-α, and cell fragments negatively affect renal tubular epithelial cells." (PMID 36632449, 2023). "For example, one study revealed fecal SCFAs levels were significantly downregulated in a rat sepsis model induced by CLP, while the levels of TNF-α, IL-1β, IL-6, and other inflammatory factors in the hippocampus were markedly upregulated." (PMID 37869005, 2023). "The serum levels of pro-inflammatory cytokines IL-1β, IL-6, and TNF-α were significantly increased after sepsis, and down-regulated by inhibiting MAPK14 to 56.7%, 64.8%, and 72.6% compared with the sepsis group, respectively." (PMID 37180171, 2023). "Plasma levels of TNF-α and IFN-γ are also markedly increased in patients with sepsis and in animal models." (PMID 37372931, 2023). "In a rat model of sepsis-induced AKI, paeonol treatment showed protective effects by lowering serum levels of TNF-α and IL-1β and suppressing NF-κB signaling in renal tissue." (PMID 36744251, 2023). "All three glial types responded with secretion of the pro-inflammatory cytokines IL-12, TNF-α, IL-1β, IL-17 and IFN-γ, which are also secreted at high levels in mouse models of S. agalactiae sepsis." (PMID 35281448, 2022). "In a cohort of 156 sepsis patients of whom 41 with ALI and 32 with ARDS, miR-155 levels are higher in patients with ALI or ARDS, positively correlate with IL-1β and TNF, and negatively correlate with PaO2/FiO2 ratio." (PMID 35990654, 2022). "To address this, we comparatively measured the level and cost-effectiveness of sepsis biomarkers such as DNI, MPO, PCT, and, TNF-α in a CLP-induced sepsis mouse model mimicking human sepsis." (PMID 35334545, 2022). "Previous studies comparing models of sepsis induced by LPS injection with CLP-induced sepsis demonstrate that the inflammatory mediators such as IL-6, TNF-α, KC, and MIP-2 show different time profiles." (PMID 35648977, 2022). "In our study, an early release of TNF-α at 6 h was noted, while the time-dependent kinetics of other detected biomarkers (IL-10, bET and HMGB1) were consistent with sepsis progression." (PMID 35615093, 2022). "Mice with LPS-induced-sepsis who were treated with BPF had lower serum levels of IL-6, TNF-α, IL-1β, CXCL1, and CXCL2 than the control mice treated with BPF." (PMID 36361915, 2022). "Rs12196996 GG and rs2232365 AA were also correlated with increased level of miR-23a, IL-10 and decreased level of TNF, IL-2, IFN, IL-6 and IL-1β in the peripheral blood cell samples of patients with ICU-acquired sepsis." (PMID 35156517, 2022). "The expression of iNOS, COX-2, TNF-α, IL-6, and HMGB-1 is inhibited following phlorotannin treatment in a lipopolysaccharide-induced sepsis model." (PMID 35597942, 2022). "Third, the cost-effectiveness between sepsis biomarkers indicated that the rank of clinically applicable biomarkers is DNI, PCT, TNF-α, and MPO in descending order." (PMID 35334545, 2022). "And the level of pro-inflammatory cytokines including (TNF-α and IL-1β) were further elevated in LysM+QKIfl/fl mice after TGX-221 treatment in MRSA induced sepsis." (PMID 36088389, 2022). "The plasma levels of TNF-α, IL-6, and IL-1β in the T2DM combined with the sepsis group were significantly higher than those in the control group (P < .001)." (PMID 35960063, 2022). "Sepsis-induced T lymphocyte alterations were characterized by a decreased cytokine production (mainly of IFN-γ and/or TNF-α, mostly for CD4+ T cells) and a decreased proliferation capacity (for both CD4+ and CD8+ T cells)." (PMID 36045686, 2022).
Sepsis (continued). "Collectively, these data indicate that DNI in CLP-induced sepsis mice is as effective as the existent inflammatory biomarkers such as MPO, PCT and TNF-α to predict the prognosis of sepsis." (PMID 35334545, 2022). "This is in contrast to the results of meta-analyses of data from in vitro cell culture studies of sepsis, which revealed inhibitory effects of IRAK3 on TNF-α level at IT in cell lines and at LT in mouse primary cells after one-challenge." (PMID 35167625, 2022). "In a pediatric study (n = 60/55 healthy and sepsis patients), miR-146a is decreased in blood and negatively correlated with the levels of C-reactive protein, procalcitonin (PCT), IL-6 and TNF." (PMID 35990654, 2022). "Furthermore, the overexpression of miR-22 can reduce the expression of inflammatory factors (IL-1β, IL-6, and TNF-α) and NO, as well as significantly reduce cell apoptosis via PTEN/high-mobility group Box 1 (HMGB1) and TLR4/NF-κB pathway, thereby alleviating the AKI caused by sepsis." (PMID 35464083, 2022). "Tumor necrosis factor (TNF-α) and Interleukin 1 beta (IL-1β), the most important primary pro-inflammatory mediators, are the cytokines most extensively studied in sepsis patients." (PMID 36189302, 2022). "JWH-133, which also selectively activates CB2, was shown to reduce serum IL-6 and TNFα at 24 h post-induction in cecal ligation and puncture (CLP)-induced sepsis." (PMID 36555499, 2022). "In particular, its increased expression during sepsis contributes to the suppression of macrophage migration, as well as a decrease in NFKB1 transcriptional activity and the downstream cytokines TNF-α and IL-6." (PMID 36670868, 2022). "Zingerone also lowered the plasma levels of IL-6 and TNF-α, reduced lethality due to CLP-induced sepsis, raised lipid peroxidation, and improved the antioxidant defence system by restoring the concentrations of SOD, GPX, and CAT in kidney tissues." (PMID 36588685, 2022). "In summary, we used a cytokine cocktail comprising of TNF-α, IL-1β and IFN-γ to treat different organ-specific ECs for 4 h or 24 h and modelled the cytokine-induced changes as observed in sepsis." (PMID 35955534, 2022). "naringin decreases TNF-α and HMGB1 release from LPS-stimulated macrophages and improves survival in a CLP-induced sepsis mice." (PMID 35720285, 2022). "In another study, high concentrations of IL-1β and TNF-α and a large number of cells labeled with IBA-1 were found in the early stages of sepsis in an animal model of sepsis induced by the CLP surgery." (PMID 36333747, 2022). "miR-146a-5p-mediated activation of TLR7 induces TNF, pulmonary inflammation, endothelial barrier disruption and ARDS in sepsis mice." (PMID 35990654, 2022). "The levels of TNF-α and MCP-1 in plasma of 90 patients with severe sepsis were higher than those in the controls." (PMID 36072408, 2022). "In the endotoxin tolerance process of sepsis, SIRT1 accumulates in the promoters of IL-1β and TNF-α and NAD+ levels increase, which enhances H3K16 deacetylation." (PMID 35359990, 2022). "The reactions of some pro inflammatory cytokines such as tumor necrosis factor-alpha (TNF-α), interleukin-6 (IL-6), and interleukin-10 (IL-10) have all been characterized in the situation of sepsis, surgical damage, and trauma." (PMID 35148750, 2022). "The serum levels of IL-1β, IL-6, TNF-α, and IFN-γ levels were increased in the acute phase of sepsis (one day after the surgery, CLP group) as compared with sham mice, suggesting an enhanced systemic inflammatory reaction." (PMID 36148090, 2022). "The correlation matrices in the sepsis group produced a single cluster showing a positive interaction among the pro-inflammatory mediators (CCL3, CCL4, IL1β, IL-6 and TNFα)." (PMID 35811678, 2022). "In sepsis models, S1P3−/− mice had reduced survival rates concomitant with increased inflammatory response of TNF-α and IL-6." (PMID 35094654, 2022).